ZNF8 (zinc finger protein 8)
Description:
Transcriptional repressor. May modulate BMP and TGF-beta signal transduction, through its interaction with SMAD proteins.
Synonyms: HF.18; Zfp128
Tractability: PROTAC: UniProt records ubiquitination sites on it; ubiquitination databases record sites on it; its protein half-life has been measured.
Gene: Protein-coding gene on chromosome 19 (58,278,955 to 58,302,791, forward strand). Ensembl gene ENSG00000278129.
Subcellular location: Nucleus
Subcellular location (Human Protein Atlas): Nuclear bodies; Nucleoplasm
Gene Ontology:
Molecular function: protein binding; DNA binding; DNA-binding transcription factor activity, RNA polymerase II-specific; RNA polymerase II cis-regulatory region sequence-specific DNA binding; zinc ion binding
Biological process: regulation of transcription by RNA polymerase II; regulation of DNA-templated transcription
Cellular component: nucleus
Genetic constraint (gnomAD): Loss-of-function variants: 9 observed, 11.91 expected, observed/expected ratio (o/e) 0.76, 90% interval 0.45 to 1.32. The upper end of that interval is the gene's LOEUF score, 1.32, which puts it in group 5 of 6, group 1 being the genes least tolerant of losing a copy. Missense variants: 664 observed, 754.05 expected, observed/expected ratio (o/e) 0.88, 90% interval 0.82 to 0.94. Synonymous variants: 274 observed, 293.88 expected, observed/expected ratio (o/e) 0.93, 90% interval 0.84 to 1.03.
Homologues: Orthologues: chimpanzee ZNF8 (99% identical), macaque ZNF8 (95% identical), dog ZNF8 (82% identical), rabbit ZNF8 (80% identical), rat LOC108348304 (74% identical), mouse Zfp128 (73% identical), pig ZNF8 (64% identical), guinea pig ZNF8 (58% identical). Paralogues in human: ZNF551 (32% identical), ZNF792 (31% identical), ZNF304 (31% identical), ZNF256 (31% identical), ZNF570 (30% identical), ZNF583 (30% identical), ZNF587B (30% identical), ZNF549 (30% identical), ZNF548 (29% identical), ZNF480 (29% identical), ZNF79 (28% identical), ZSCAN20 (28% identical), and 26 more.
Diseases named in the same sentence as ZNF8 in open-access papers:
ZNF8 is named in the same sentence as 7 diseases in open-access papers, as found by Europe PMC text mining. Sharing a sentence is not in itself a finding about the gene and the disease. The quoted sentences say what the papers report.
breast carcinoma (3 papers, 2022 to 2025). "As described in the previous sections, ZNF8 is a novel Smad3 interaction protein and was associated with the lung metastasis of breast cancer." (PMID 39225541, 2024). "Our further results revealed that the family member ZNF8, a novel Smad3 cofactor, was associated with the prognosis of lung metastasis in patients with breast cancer." (PMID 39225541, 2024). "This highlights the potential of targeting the TGF‐β pathway through ZNF8 as a promising strategy for addressing breast cancer lung metastasis." (PMID 39225541, 2024). "We next sought to investigate the molecular mechanism by which ZNF8 regulates the TGF‐β pathway to promote breast cancer metastasis." (PMID 39225541, 2024). "In this study, we screened in human breast cancer cells and identified the transcription factor ZNF8 as a novel protein that interacts with Smad3, which is a well‐known mediator of the TGF‐β pathway." (PMID 39225541, 2024). "Survival analysis of LMSF also revealed that mice in the TGF‐β1 treatment group were more prone to lung metastasis by breast cancer cells, and ZNF8 knockout almost completely suppressed this effect." (PMID 39225541, 2024). "To further investigate the ability of ZNF8 to promote breast cancer metastasis, we generated conditional mammary epithelium cell‐specific ZNF8 knockout mice (MMTV‐Cre; Znf8fl/fl)." (PMID 39225541, 2024). "After further analysis of transcription factors, ZNF8 was identified because of its significant correlation with the prognosis of patients with breast cancer." (PMID 39225541, 2024). "This study first establishes the interactome of Smad3 in breast cancer cells and identifies ZNF8 as a novel Smad3 cofactor." (PMID 39225541, 2024). "We also isolated the tumor cells from the lung metastasis lesion of WT and KO mice and conducted Transwell analysis, and the results showed the migration and invasion abilities of breast cancer cells were markedly decreased in ZNF8 knockout tumor cells." (PMID 39225541, 2024). "TGF‐β1 treatment significantly amplified ZNF8‐mediated promoting of cell migration, whereas ZNF8‐mediated breast cancer cell migration and invasion were significantly suppressed by SB431542 treatment." (PMID 39225541, 2024). "Considering the significant prognostic value of ZNF8 for breast cancer, we conducted a series of studies to further evaluate the clinical correlation of ZNF8 with multiple cohorts of breast cancer patients." (PMID 39225541, 2024). "We also demonstrated that ZNF8, a Smad3‐interacting protein, is indispensable for multiple processes related to lung metastasis in breast cancer by epigenetic modulation." (PMID 39225541, 2024). "Considering that most of the prometastatic genes regulated by ZNF8 encode secreted proteins, we examined the effects of conditioned media obtained from cultured breast cancer cells with different ZNF8 expression levels." (PMID 39225541, 2024). "Our studies confirmed that ZNF8, which interacts with Smad3, plays a critical role in the regulation of breast cancer metastasis via TGF‐β through SMYD3." (PMID 39225541, 2024). "Furthermore, the results reveal that ZNF8 is closely associated with breast cancer lung metastasis prognosis, and specifically facilitates TGF‐β pathway‐mediated breast cancer lung metastasis by participating in multiple processes." (PMID 39225541, 2024). "Notably, ZNF8 promoted lung metastasis in breast cancer by facilitating multiple processes, including EMT, cell migration and invasion, endothelial adhesion, extravasation from vessels, and neutrophil infiltration in primary tumors and lungs." (PMID 39225541, 2024). "Furthermore, treatment with BCI121 effectively suppressed the ZNF8‐induced increase in the metastatic potential of breast cancer cells." (PMID 39225541, 2024). "Moreover, ZNF8 knockout also hindered the TGF‐β pathway‐promoted adherence of breast cancer cells to HUVECs." (PMID 39225541, 2024).
breast carcinoma (continued). "Moreover, our clinical studies suggested that the prognostic significance of SMYD3 in breast cancer is influenced by ZNF8 expression, further highlighting the key role of ZNF8 in this axis." (PMID 39225541, 2024). "Overall, ZNF8 promoted lung metastasis of breast cancer by influencing multiple processes." (PMID 39225541, 2024). "Additionally, we performed functional rescue experiments by transfecting full‐length ZNF8 and its C‐terminal deletion mutant into ZNF8 knockout breast cancer cells." (PMID 39225541, 2024). "Therefore, our results confirmed that ZNF8 promoted the transcriptional activation of lung metastasis signature genes by recruiting SMYD3 subsequently promoting breast cancer metastasis." (PMID 39225541, 2024). "Additionally, the inhibitory effects of BCI121 on the transcription of lung metastasis signature genes, cell migration, and invasion were nearly eliminated in ZNF8 knockout breast cancer cells." (PMID 39225541, 2024). "In vivo, we observed that the rhodamine signal in the lung tissue of mice injected with ZNF8 knockout cells was significantly lower than that in the lung tissue of control mice, indicating that ZNF8 plays a substantial role in enhancing the extravasation capability of breast cancer cells." (PMID 39225541, 2024). "The conditioned media derived from ZNF8‐overexpressing and ZNF8 knockout cells suppressed the invasion abilities of breast cancer cells, indicating that ZNF8 could promote cancer cell invasion through cell‐autonomous and non‐cell‐autonomous mechanisms simultaneously." (PMID 39225541, 2024). "Our results confirmed that targeting SMYD3 can inhibit ZNF8‐mediated invasion and metastasis of breast cancer cells, indicating that targeting the mechanism by which ZNF8 recruits SMYD3 may be an effective strategy for the TGF‐β‐mediated lung metastasis of breast cancer." (PMID 39225541, 2024). "Therefore, ZNF8 is a new Smad3 cofactor that involved in multiple steps of breast cancer lung metastasis, and targeting ZNF8 may be a potential strategy for preventing breast cancer lung metastasis." (PMID 39225541, 2024). "In addition, blocking SMYD3 with BCI121 inhibited ZNF8‐mediated lung metastasis in breast cancer." (PMID 39225541, 2024). "Until now, very few functions of ZNF8 has been reported, including regulating BMP signaling 36 and controlling the progression of gastrointestinal 37 and breast cancer." (PMID 40162224, 2025). "The interaction between ZNF8 and Smad3 was confirmed in MDA‐MB‐231, MCF‐7, and T47D breast cancer cells by co‐immunoprecipitation (Co‐IP), which also showed that the interaction was enhanced after TGF‐β pathway activation." (PMID 39225541, 2024). "To further confirm the biological roles of ZNF8 in breast cancer, we generated ZNF8 knockout MDA‐MB‐231 and Hs578T cells and ZNF8‐overexpressing ZR‐75‐1 and MCF‐7 cells." (PMID 39225541, 2024). "In conclusion, our results demonstrated the indispensable role of ZNF8 in TGF‐β‐induced EMT and metastasis in breast cancer." (PMID 39225541, 2024). "Then, these mice were crossed with MMTV‐PyMT transgenic mice, a classic spontaneous mammary tumor model, to obtain Znf8fl/fl; MMTV‐ PyMT (WT), Znf8 fl/fl; MMTV‐Cre; MMTV‐PyMT (KO) and heterozygous knockout mice (Znf8fl/+; MMTV‐Cre; MMTV‐PyMT (Het))." (PMID 39225541, 2024). "In upregulated mRNAs in breast cancer tissue, EPN3 was up-expressed as the cancer progressed, and ZNF8 was down-expressed as the cancer progressed." (PMID 36294892, 2022). "Furthermore, knocking out ZNF8 significantly inhibited the TGF‐β1‐induced transcription of lung metastasis signature genes and the migratory and invasive properties of breast cancer cells." (PMID 39225541, 2024). "Moreover, the cell proliferation and colony formation assay results indicated that ZNF8 did not significantly affect the proliferation or colony formation abilities of breast cancer cells, which was consistent with the in vivo results." (PMID 39225541, 2024).
breast carcinoma (continued). "Moreover, SMYD3 expression was significantly negatively correlated with poor breast cancer prognosis in patients with high ZNF8 expression but not in patients with low ZNF8 expression." (PMID 39225541, 2024). "Thus, our findings suggest that ZNF8 acts as a selective coactivator of the TGF‐β/Smad3 pathway, specifically facilitating lung metastasis in breast cancer while not impacting tumor cell proliferation." (PMID 39225541, 2024).
asthma (1 paper, 2023). "This study demonstrated that two potentially novel genes (SETDB1 and ZNF8) are associated with the development of asthma, based on gene–smoking interaction analyses using multiple cohorts of the KoGES consortium." (PMID 37569643, 2023). "Using follow-up bioinformatics analyses, we also confirmed that two novel genes (SETDB1 and ZNF8) and three previously reported genes (DOCK8, MMP20, and ADCY9) are potential asthma-associated genes." (PMID 37569643, 2023). "We identified two potentially novel (SETDB1 and ZNF8) and five previously reported (DM4C, DOCK8, MMP20, MYL7, and ADCY9) genes associated with increased asthma risk." (PMID 37569643, 2023).
breast tumors (1 paper, 2024). "Moreover, BCI121 significantly suppressed the spontaneous lung metastasis of breast tumors in the transgenic animal study, but this effect was also absent in ZNF8 conditional knockout mice." (PMID 39225541, 2024).
metastatic tumors (1 paper, 2024). "However, the impact of ZNF8 on the growth of orthotopic tumors was nonsignificant, as the tumor cells isolated from orthotopic and lung metastatic tumors from the ZNF8 knockout group and the control group displayed the same proliferative capacity." (PMID 39225541, 2024).
tumor (2 papers, 2022 to 2024). "Concomitantly, in vitro vascular permeability experiments revealed that ZNF8 knockout significantly inhibited the ability of the tumor cells to disrupt the integrity of the HUVEC monolayer." (PMID 39225541, 2024). "Endothelial cell attachment and transendothelial migration are the key steps for tumor cell metastasis to the lung, and we next investigated the effects of ZNF8 on these processes." (PMID 39225541, 2024). "Notably, Gene Set Enrichment Analysis (GSEA) of the tumor proteome revealed that ZNF8 expression level was positively correlated with chemotaxis in primary tumors." (PMID 39225541, 2024). "However, histological analysis revealed that the tumor grade of ZNF8 knockout mice was significantly lower than that of the mice in the other two groups." (PMID 39225541, 2024). "Interestingly, in lung tissues collected from mice during the early stage of lung metastasis (20 weeks), ZNF8 promoted neutrophil infiltration more significantly than it did in the primary tumor." (PMID 39225541, 2024). "However, there have been very few tumor-related studies on ZNF8, and its function is not clearly known." (PMID 36294892, 2022).
ZNF8 also shares sentences with these, for which no sentence is quoted: cancer (2 papers); lymph node metastasis (1).